ENSG00000274055
Gene: Miscellaneous RNA gene on chromosome 9 (22,046,758 to 22,046,901, forward strand). Ensembl gene ENSG00000274055.
Gene Ontology:
Biological process: heterochromatin formation